INS (insulin)
Diseases named in the same sentence as INS in open-access papers (continued):
Sharing a sentence is not in itself a finding about the gene and the disease.
Hyperglycemia (continued). "This elevated insulin output enhances glucose uptake in skeletal muscle and adipose tissue, helping to prevent hyperglycemia in the early stage." (PMID 40868096, 2025). "In this study, we investigated the effects of flow‐based co‐culturing and hyperglycemia on the circulating levels of adipokines and insulin." (PMID 40746010, 2025). "In both settings, the Gnasβcell–/– mice displayed severe glucose intolerance and a failure to increase circulating insulin in response to experimental hyperglycemia." (PMID 40526441, 2025). "Anticipatory insulin signaling, coupled with postprandial hyperglycemia, can lead to hyperinsulinemia that paradoxically drives hunger and overeating." (PMID 41305664, 2025). "Inappropriate glucagon secretion, especially a failure to suppress glucagon during hyperglycaemia, antagonises insulin and can blunt the early insulin response and dampen pulsatility." (PMID 41226286, 2025). "Bexagliflozin reduced insulin dose and improved glycemic control in combination with insulin in five poorly controlled diabetic cats and controlled hyperglycemia and clinical signs as the sole therapy in 68 out of 84 (81%) cats with newly diagnosed DM." (PMID 40853201, 2025). "For FG > 500 mg/dL (27.8 mmol/L) or life-threatening complications of hyperglycemia at any FG level, withhold capivasertib and initiate aggressive hydration, electrolyte management, and insulin (0.1 μ/kg/h), as needed." (PMID 41345397, 2025). "Hyperglycaemia and insulin excess potentiate leptin-mediated signalling, particularly via IGF1R–Akt–mTOR activation, further accelerating cell cycle progression and biomass accumulation in breast and mammary epithelial cells." (PMID 41586225, 2025). "Following the amelioration of inflammation and oxidative stress in T2DM patients, insulin sensitivity and β-cell function can be enhanced, the insulin signaling pathway is preserved, and hyperglycemia can be better controlled." (PMID 40842498, 2025). "Studies indicate that women with PCOS exhibit impaired incretin response, particularly reduced GLP-1 secretion and diminished GLP-1 receptor (GLP-1R) expression in pancreatic β-cells, contributing to insufficient postprandial insulin release and hyperglycemia." (PMID 40076938, 2025). "Specifically, co‐culturing enhancements were more dramatic under hyperglycemia (12.5 and 25 mm) conditions, with corresponding increases in insulin secretion." (PMID 40746010, 2025). "Conversely, certain viruses induce hyperglycemia by targeting hepatocytes to trigger gluconeogenesis or infecting β-cells to impair insulin secretion (5, –, 8)." (PMID 40391966, 2025). "Hyperglycemia is a stress response secondary to glycogenolysis and can be compounded by insulin dysregulation and preexisting equine metabolic disorders." (PMID 40895787, 2025). "It has also been shown to decrease the ability of insulin to suppress hepatic glucose production, thereby contributing to hyperglycemia." (PMID 40870963, 2025). "In 60.4% of hyperglycemic patients, hyperglycemia persisted during hospitalization; 12.4% required insulin therapy for glycemic control." (PMID 41156159, 2025). "Secondary contributors like hyperglycemia and reduced physical activity further decrease insulin sensitivity." (PMID 41323015, 2025). "The AKT pathway plays an important role in response to insulin and represents protection against hyperglycemia." (PMID 40277891, 2025). "This disruption in the response to insulin leads to disrupted glucose metabolism and dysfunction of β-cells, resulting in increased blood glucose or hyperglycemia." (PMID 40809178, 2025). "Maternal adiposity is associated with increased leptin production, hyperinsulinemia, and hyperglycemia, leading to fetal hyperglycemia and excessive insulin secretion." (PMID 40243644, 2025). "This indicates that intermittent fasting aids in controlling hyperglycaemia by maintaining insulin sensitivity." (PMID 39861423, 2025).
Hyperglycemia (continued). "Hyperglycaemia is usually corrected with rapid‐acting insulin, which can have variable onset and duration of action, especially in the context of recent meals or activity, leading to inconsistent glucose responses." (PMID 41059660, 2025). "This also leads to systemic insulin and different metabolic disturbances such as hyperglycemia, hypertension, increased blood lipids, and NAFLD." (PMID 39859066, 2025). "Glucocorticoids exacerbate hyperglycemia through several mechanisms such as hepatic glucose production, protein catabolism, impaired insulin secretion, and glucose uptake of the peripheral tissues." (PMID 40230621, 2025). "Hyperglycemia in neonatal sepsis likely results from increased hepatic gluconeogenesis and insulin resistance, both of which are part of the adaptive metabolic response to inflammation and infection." (PMID 41209349, 2025). "More specifically, PXJ significantly reduced HFFD-induced hyperglycemia and improved insulin levels." (PMID 41041136, 2025). "He showed that within one week after bariatric surgery, correction of hyperglycemia was accompanied by the rapid correction of hyperinsulinemia and lowering of fasting insulin levels." (PMID 41009753, 2025). "Our findings revealed that MFLX induced hyperglycemia in diabetic rats, with a more pronounced reduction in serum insulin,GLP-1, and FGF15 levels than observed in normal rats." (PMID 40255568, 2025). "The inability of pancreatic beta cells to match the increased insulin resistance to normalize the systemic glucose level translates to maternal hyperglycemia." (PMID 41356011, 2025). "Both types lead to hyperglycemia due to the compromised uptake of glucose by the insulin targets in the periphery." (PMID 40585503, 2025). "The pathophysiological mechanism of the disorder includes the development of maternal hyperglycemia due to inadequate insulin secretion, typically accompanied by insulin resistance during the second or third trimester of pregnancy." (PMID 41007128, 2025). "Endocrinology referrals are warranted for persistent hyperglycemia, escalating insulin needs, or recurrent hypoglycemia." (PMID 40564201, 2025). "When conditions change (including pH, temperature, and ionic strength) or after postprandial hyperglycemia, these complexes destabilize and dissociate, releasing free insulin and IAA." (PMID 41585798, 2025). "Twenty-three patients (52.27%) developed AKI, and 29 individuals (65.90%) had hyperglycemia requiring i.v. or s.c. insulin administration." (PMID 41306809, 2025). "MiR206 is suggested to not only prevent both NAFLD and hyperglycemia progression but also inhibit Srebp1c-induced lipogenesis and activate the insulin signaling pathway." (PMID 40002783, 2025). "She first presented at the age of 50 days with hyperglycemia (750 mg/dL) and metabolic acidosis requiring high‐dose insulin infusion therapy (2 units/kg/h)." (PMID 41424588, 2025). "The primary therapeutic method for correcting hyperglycemia was dietary therapy, which involved excluding easily digestible carbohydrates (patients who required a switch to insulin therapy were excluded from further study)." (PMID 39940917, 2025). "With prolonged impairments in insulin sensitivity, a subsequent failure of pancreatic islets will occur as a result of its attempts to compensate for this persistence in hyperglycemia by maintaining the production of insulin." (PMID 41210503, 2025). "Sliding scale insulin regimes involve s.c. administration of soluble insulin when hyperglycaemia is detected." (PMID 40480914, 2025). "After hospital admission the insulin regimen had converted to insulin analogues, rapid‐acting (aspart) and long‐acting (glargine), for more precise BS control; however, she still had episodes of hypo and hyperglycemia." (PMID 41235379, 2025). "We have previously published that intensive insulin management has subphenotype-specific beneficial effects among children with hyperglycemia accompanying cardiorespiratory failure." (PMID 41041556, 2025).
Hyperglycemia (continued). "Insulin is the preferred choice over oral antidiabetic agents for managing glucocorticoid‐induced hyperglycemia, particularly in significant hyperglycemia and severe illness." (PMID 40931439, 2025). "Insufficient insulin secretion is a key factor in hyperglycemia, and protecting pancreatic islet cells is crucial for promoting insulin production." (PMID 41561166, 2025). "Despite presenting with less severe initial hyperglycemia, ketonemia and acidemia, the SGLT2i group required a significantly greater amount of insulin to achieve a comparable resolution time of acidemia and ketonemia compared to the non-SGLT2i group." (PMID 40843859, 2025). "This connection can be explained by the impact of hyperglycemia, high insulin levels and insulin resistance on the activation of the IGFR1-IR-PI3K-AKT-mTOR pathway, which is considered a cause of carcinogenesis." (PMID 40149994, 2025). "According to previous reports, in GCK-hyperglycemia pregnant patients supraphysiological insulin doses (>1 unit/kg/day) are usually required to overcome maternal counterregulatory mechanisms." (PMID 41409604, 2025). "These inflammatory mediators disrupt insulin signaling pathways and compromise pancreatic β-cell function, exacerbating hyperglycemia." (PMID 40416377, 2025). "The management of DKA is centered on correction of fluid deficits, electrolyte imbalances, and hyperglycemia, traditionally achieved through aggressive intravenous fluid resuscitation and insulin therapy." (PMID 41262789, 2025). "Diabetic ketoacidosis (DKA) is a life-threatening condition, and treatment consists of aggressive fluid replacement and correcting the insulin deficit to resolve the acidosis and hyperglycemia." (PMID 40978981, 2025). "Hyperglycemia and the reduction in the production and/or action of insulin culminate in a deep hormonal imbalance in diabetic patients, including the hyperactivity of the hypothalamus-pituitary-adrenal (HPA) axis." (PMID 40496562, 2025). "Advanced glycation end products (AGEs), which accumulate in insulin-resistant states due to chronic hyperglycemia, exacerbate lymphatic dysfunction." (PMID 41403736, 2025). "For instance, the cardio–renal–metabolic axis links hyperglycemia and insulin resistance to maladaptive kidney activation of the renin–angiotensin–aldosterone system (RAAS), which in turn worsens cardiac remodeling and vascular stiffness." (PMID 41010881, 2025). "Our simple model of β-cell adaptation neglects the known hyperglycemia-induced leftward shift in the insulin secretion curve (f(G) in Eq." (PMID 38895272, 2025). "Similar to other viruses, SARS-CoV-2 infection may induce a stress response that reduces insulin production, releases counterregulatory hormones, including cortisol and adrenaline, induces excessive gluconeogenesis and impairs glucose disposal, thereby causing transient hyperglycemia." (PMID 40469441, 2025). "Compared to women without a history of GDM, those with such a history exhibit lower insulin sensitivity and impaired β-cell function, leading to subclinical hyperglycemia in their second pregnancy." (PMID 39963281, 2025). "Among current approaches, phenylboronic acid‐based formulations represent a leading strategy due to their reversible glucose‐binding capacity; these compounds activate insulin release upon hyperglycemia and automatically deactivate when glucose normalizes." (PMID 40919135, 2025). "Supporting this, a Saudi study found that insulin pumps with sensors significantly reduced both hyperglycemia and hypoglycemia in female patients after six months, particularly in those with a shorter duration of T1DM." (PMID 41250728, 2025). "Insulin therapy is especially beneficial for patients with concurrent hyperglycemia and hypertriglyceridemia, as it addresses both conditions simultaneously." (PMID 39958046, 2025). "HYA also ameliorated postprandial hyperglycemia in type 1 diabetes model rats injected with bolus insulin before OGTT." (PMID 39899133, 2025).
Hyperglycemia (continued). "Tissue remodeling is also affected, as fibroblasts exhibit reduced collagen synthesis and improper extracellular matrix remodeling due to both hyperglycemia and impaired insulin signaling." (PMID 40280905, 2025). "Type 1 diabetes is a devastating autoimmune disease—characterized by the destruction of insulin-producing beta cells in pancreatic islets, resulting in hyperglycemia—that affects 8.75 million people worldwide." (PMID 41226824, 2025). "Insulin resistance (IR) is characterized by reduced tissue sensitivity to insulin, resulting in hyperglycemia and activation of alternative metabolic pathways." (PMID 41257140, 2025). "Elevated levels of progesterone, predominant in the luteal phase, can impair insulin sensitivity, resulting in premenstrual hyperglycemia and augmented insulin secretion." (PMID 40535039, 2025). "In the ICU set, IS patients are at a higher risk of dramatic blood sugar fluctuations and stress-induced hyperglycemia due to the dual effects of stress-induced insulin resistance and sympathetic nervous system activation." (PMID 41291553, 2025). "Pancreatic β-cells were historically considered a homogeneous population, defined primarily by insulin synthesis and secretion in response to hyperglycemia." (PMID 41584842, 2025). "Hyperglycemia is accompanied by compensatory endogenous insulin overproduction, potentially resulting in hypoglycemic episodes or cerebral and peripheral insulin resistance." (PMID 40198816, 2025). "HF and DM share a bidirectional relationship, with new-onset diabetes (often referred to as cardiogenic diabetes) being common in HF patients due to increased insulin resistance and a reduced insulin secretory response of pancreatic β-cells to hyperglycemia." (PMID 40470769, 2025). "An infant female (case 20), 14 days old, presented with postnatal hyperglycemia reaching up to 13.4 mmol/L, diminished insulin and C-peptide levels." (PMID 40129607, 2025). "Recently published studies have proposed management strategies for glucocorticoid-induced hyperglycemia, indicating that insulin therapy is often inevitable." (PMID 40426928, 2025). "These factors likely contribute to early postprandial hyperglycemia, which stimulates an exaggerated insulin response." (PMID 40648766, 2025). "In this population, postprandial hyperglycemia is typically more pronounced than fasting hyperglycemia, primarily due to impaired early-phase insulin secretion and a diminished incretin effect." (PMID 41378215, 2025). "Individuals with LADA typically do not require insulin for at least 6 months after diagnosis, but women with hyperglycemia during pregnancy do require insulin, which remains the safest therapy option." (PMID 41020242, 2025). "Reduces hyperglycemia, ameliorates hepatic/intestinal tissue damage, and decreases glycogen accumulation via enhanced insulin signaling." (PMID 40238536, 2025). "The management of decompensated diabetic patients and DKA is multifaceted and includes intravenous fluid resuscitation, correction of electrolyte imbalances, and, critically, the administration of insulin to suppress ketogenesis and reduce hyperglycemia." (PMID 41150108, 2025). "Under conditions of elevated insulin demand, coupled with hypoxia and hyperglycaemia within the endocrine pancreas, the homeostatic UPR response is exhausted and beta cells become complicit in their own demise." (PMID 40133488, 2025). "Our previous research confirmed its ability to reduce postprandial hyperglycemia by inhibiting glucose absorption and key digestive enzymes, as well as enhancing insulin function and glucose uptake." (PMID 40548186, 2025). "•Mechanistic studies support insulin resistance of metabolic tissues as the root cause of MASLD, whereas hepatic insulin resistance in turn contributes to hyperglycemia." (PMID 41362583, 2025).
Hyperglycemia (continued). "The pathophysiology of DOP is characterized by insulin and IGF-1 deficiency, hyperglycemia, advanced glycation end products (AGEs), pro-inflammatory cytokines, and oxidative stress." (PMID 40873948, 2025). "The first involves hyperglycemia; this begins with increased food intake due to increased leptin resistance due to increase leptin levels, which in turn block insulin secretion, leading to the onset of hyperglycemia." (PMID 40356974, 2025). "In diabetic canine and mice models, it alleviated hyperglycemia, improved glucose tolerance, and enhanced pancreatic islet area and insulin secretion." (PMID 41185072, 2025). "The pathophysiological state termed IR is defined by a decreased capacity of the body to respond to and metabolize insulin, culminating in hyperglycemia." (PMID 41169465, 2025). "Type 1 diabetes (T1D) is an organ-specific autoimmune disease that results in the progressive destruction of insulin-producing pancreatic β-cells, leading to symptomatic hyperglycemia and lifelong exogenous insulin dependency." (PMID 40709181, 2025). "For short-acting glucocorticoids, such as hydrocortisone, which induce hyperglycaemia acutely and often see a similar resolution, the decision to give insulin is made on a case-by-case basis." (PMID 41567924, 2025). "The significant duration of the patient's hyperglycemia secondary to NDM highlights the importance of early genetic testing for this disease as the switch from insulin to SU was ultimately only recommended due to the insight provided by genetic testing." (PMID 40309172, 2025). "Maternal hyperglycemia likely leads to increased transplacental glucose transfer, stimulating fetal insulin production, a potent growth factor." (PMID 40464047, 2025). "The RECOVERY trial, which did find group differences in hyperglycemia, also defined it as requiring insulin." (PMID 40665171, 2025). "Glucose-stimulated insulin secretion (GSIS) was used to determine hyperglycemia induced islet stress." (PMID 41141358, 2025). "Several flavonoids have been validated to upregulate the IRS/PI3K/AKT pathway, consequently exerting anti-hyperglycemia and anti-insulin-resistance activity." (PMID 40298635, 2025). "Insulin infusion remains the gold standard for managing stress‐induced hyperglycemia in critically ill patients." (PMID 41426511, 2025). "After childbirth, especially during the immediate postpartum period, the management of women involves stopping insulin therapy and recommending fasting blood glucose tests to check for persistent hyperglycaemia." (PMID 40937115, 2025). "Postpartum, insulin sensitivity typically improves, leading to the resolution of hyperglycemia in most cases." (PMID 40076938, 2025). "In insulin resistant individuals, attenuation of this effect would result in postprandial hyperglycemia." (PMID 40631311, 2025). "Excess ROS, generated in response to chronic hyperglycemia and inflammation, can impair insulin signaling, exacerbate pancreatic β-cell damage, and disrupt GM balance." (PMID 40722870, 2025). "In the case of long‐term hyperglycemia, pancreatic islet cells will work in compensation, which will lead to IR, insufficient insulin secretion, and ultimately lead of DM." (PMID 41476996, 2025). "Corticosteroids as a component of cancer treatment regimen are likely to reduce the insulin sensitivity and subsequent onset of hyperglycemia and diabetes, as well as influence the lipid metabolism." (PMID 40735043, 2025). "Metabolic dysregulation that contributes to hyperglycemia includes decreased insulin secretion, impaired glucose utilization, or increased glucose production and eventually causes pathophysiological changes in multiple organs and systems." (PMID 41012462, 2025). "Further analysis of studies using much higher doses of MH (above 1000 mg/kg) in rats revealed that such exposure led to hyperglycemia and a decrease in insulin levels." (PMID 41515170, 2025).